CD34 (CD34 molecule)
Diseases named in the same sentence as CD34 in open-access papers (continued):
Sharing a sentence is not in itself a finding about the gene and the disease.
malaria (8 papers, 2011 to 2020). Malaria is a serious and sometimes fatal disease caused by a parasite that commonly infects a certain type of mosquito which feeds on humans. "One article has also reported that malaria can cause an imbalance in the globin expression by using the CD34+ haematopoietic stem cell culture system." (PMID 31681806, 2019). "Here, we have demonstrated that CD34+ cord blood-derived iPSCs and forebrain organoids can be utilized to study malaria-induced heme-mediated and other pathogen-induced brain injuries." (PMID 31844087, 2019). "We found increased CD34+ cells, which might contribute to the repair of malaria parasite-induced tissue injury." (PMID 33298881, 2020). "Here we show that infusion of MSCs isolated from malaria-infected mice protects recipient animals from malaria infection, induces CD34+ cells in secondary lymphoid organs, restores erythropoiesis by upregulation of GATA-1, and restores T cells by lymphopoiesis." (PMID 33298881, 2020). "These cells are derived from CD34+ hematopoietic stem and progenitor cells, and these stem cell populations are depleted in individuals with severe malaria by an unknown mechanism." (PMID 26555697, 2015). "We hypothesized that CD34+-HSPC depletion during malaria pathogenesis is a function of heme-induced apoptosis mediated by induction of CXCL10 and TLR activation." (PMID 26555697, 2015). "Our results indicate that free heme is a major contributor to severe malaria pathophysiology by inducing apoptosis in HBVEC and CD34+-HSPC, which are vital BBB cellular components." (PMID 26555697, 2015). "We have shown that integral components of the BBB, specifically HBVEC and CD34+-HSPC, are activated to increase expression of TLR4 in addition to excess CXCL10 production in the presence of increased heme, which mimics in vivo conditions in malaria." (PMID 26555697, 2015). "The effect of human malaria on the development of HSCs is not known and whether the prolonged CD34+ HSC propagation in vitro was due mainly to activation by P. falciparum-infected erythrocytes requires further investigation." (PMID 28347310, 2017). "Infants from the malaria-endemic area had higher overall numbers of CD19+ B cells but reduced populations of circulating IgD+CD27+ memory B cells and expanded populations of CD10+CD34- immature transitional B cells at all ages relative to infants living in an area with unstable malaria transmission." (PMID 22166136, 2011).
mesothelioma (8 papers, 2011 to 2026). A usually malignant and aggressive neoplasm of the mesothelium which is often associated with exposure to asbestos. "All specimens were positive for CD34 (which helps to differentiate SFT from mesothelioma)." (PMID 22014289, 2011). "According to immunohistochemical analysis, SFT of the pleura is positive for vimentin, CD34, CD99, and Bcl2, which are markers of mesenchymal cells; but it is negative for cytokeratin, which is found in mesotheliomas." (PMID 21958732, 2011).
myopericytoma (8 papers, 2013 to 2025). A usually slow growing, subcutaneous nodular neoplasm arising from myopericytes. "In IHC of myopericytoma, α-SMA and h-caldesmon are positive, while desmin and CD34 show focal positivity." (PMID 40599523, 2025). "Although, myopericytoma is reported to be negative for CD34 in most cases, one case of strong and three cases of partial reactivity have been reported in the kidney." (PMID 28214470, 2017). "The majority of myopericytoma cases, including the current case, are negative for CD34, a result which differs from that of another case previously reported in the literature." (PMID 24348865, 2014).
peripheral arterial disease (8 papers, 2014 to 2023). A disorder of the arteries supplying the upper and lower extremity and the visceral organs. "Patients with peripheral arterial disease had reduced levels of CD34+/KDR+ cells." (PMID 24782825, 2014). "A study on diabetic patients with amputation as only option for severe peripheral arterial disease (PAD), evaluated the combination of intramuscular administered allogeneic UCB-MSC and CD34+ hematopoietic stem cells with intralesional implantation of allogeneic foreskin fibroblasts." (PMID 35586557, 2022). "PbMNCs from diabetic foot patients with peripheral arterial disease (PAD) without wounds and diabetic patients with wounds were comparable in terms of cell number, fold‐increase after QQc, vasculogenic potential, cell proliferation, and the presence of cell surface CD34 or CD206." (PMID 33599112, 2021).
polycythemia vera (8 papers, 2013 to 2024). "Similarly, PDE4A expression decreased in CD34+ granulocytes taken from patients with essential thrombocytopenia, polycythemia vera, and primary myelofibrosis." (PMID 38514754, 2024). "Furthermore, the promoter region of miR-16-2, which is present in a cluster with miR-15b located on chromosome 3q25, is methylated in polycythemia vera CD34+ cells." (PMID 27195958, 2016). "This case report illustrates that hairy cell leukemia in a patient with polycythemia vera may be interpreted as secondary myelofibrosis, that monocytopenia could have raised the suspicion of hairy cell leukemia earlier, and that AML does not always present with CD34-positive blasts." (PMID 29685167, 2018).
scleroderma (8 papers, 2011 to 2024). Scleroderma is a rare autoimmune connective tissue disorder characterized by abnormal hardening of the skin and, sometimes, other organs. "In scleroderma, we show the coexpression of CD34 and αSMA in some stromal cells, which suggests the participation of CD34+SCs/TCs as a source of myofibroblasts in this lesion." (PMID 34298962, 2021). "CD90+ fibroblasts have been shown to be generated and replaced by a steady-state CD34+ network in scleroderma, and the findings suggested that most scars exhibit a CD90diffuse/CD34negative/minority pattern, and dual CD90+ /CD34+ fibroblasts were observed in 91% of scars." (PMID 36747131, 2023). "Using double immunofluorescence labelling for CD34 and αSMA, we observed coexpression of both markers in stromal cells of scleroderma, which supports the notion that resident CD34+SCs/TCs may be a source of myofibroblasts in this lesion." (PMID 34298962, 2021). "When we characterized these cells in terms of ColI and CD34 expression, we found statistically significant differences (P < 0.05) between scleroderma and normal PBMCs in CD11b+/CD14+/ColI+-expressing, CD11b+/CD14+/CD34+/ColI+-expressing and CD11b+/CD14-/CD34+/ColI+-expressing cells." (PMID 21722364, 2011).
smooth muscle tumor (8 papers, 2011 to 2026). A benign or malignant myomatous neoplasm arising from smooth muscle. "Esophageal schwannoma cells were positive for S100 protein but negative for smooth muscle markers such as actin and desmin, which were positive in smooth muscle tumors, while CD34 and CD117 were characteristically positive in GIST." (PMID 40308497, 2025). "Desmin and α-SMA are used to exclude smooth muscle tumors, and CD34 and CD117 (c-kit) are used to exclude GIST." (PMID 21418642, 2011). "GISTs were difficult to diagnose and treat previously; however, now, they are diagnosed and differentiated from smooth muscle tumors with the help of immunohistochemistry, KIT, and CD34 positivity." (PMID 41497126, 2026).
systemic lupus erythematosus (8 papers, 2010 to 2025). An autoimmune multi-organ disease typically associated with vasculopathy and autoantibody production. "The results revealed that the high expression of IGKV2D-30 and CD34 was enriched in pathways, such as chemokine signaling pathway, focal adhesion, systemic lupus erythematosus, et cetera." (PMID 41333919, 2025). "Thus, the SLE CD34+ transcriptomic profile is more reminiscent of murine lupus CMPs than murine lupus LSK." (PMID 31780527, 2020). "A 2013 publication showed a reduced relapse incidence in systemic lupus erythematosus (SLE) patients undergoing AHSCT with CD34+ selection (11 vs. 68%); however, a greater proportion of the non-graft selected patients had received a low-intensity conditioning regimen." (PMID 29593711, 2018). "Sun and colleagues recently reported that CD34+ stem cells from patients with SLE had abnormal expression of CD166 and CD123 and that these abnormalities correlated with the overall lupus disease activity." (PMID 20478074, 2010). "Collectively, human CD34+ cells from patients with SLE display more commonalities in their transcripthmic profile with murine lupus CMPs rather than LSK." (PMID 31780527, 2020). "pre-EPC, EPC and mature EPC (mEPC) populations were quantified by flow cytometry analyzing their differential CD34, CD133 and VEGFR2 expression in blood samples from 120 RA patients, 52 healthy controls (HC), and 83 systemic lupus erythematosus (SLE) patients as disease control." (PMID 24465874, 2014).
T-cell lymphoma (8 papers, 2010 to 2025). "Upon differentiation of an HTLV-1 infected CD34+ HPC, the alteration of miRNA levels may favor T-cell differentiation, as recently demonstrated by the exclusive development of CD4+ mature T-cell lymphomas in HU-SCID mice reconstituted with CD34+ HPCs infected ex vivo with HTLV-1." (PMID 20132553, 2010). "However, ALP may help distinguish CD34+ AL from B and T cell lymphomas." (PMID 41137732, 2025). "Recent data from our laboratory demonstrates that ex vivo infection of CD34+ HP/HSCs with HTLV-1 reproducibly and consistently results in development of a CD4+ T-cell lymphoma in HU-SCID mice." (PMID 20132553, 2010). "This case was initially diagnosed as a T cell lymphoma, possibly with a lymphoblastic subtype; however, further immunohistochemistry was negative for immature T cell markers, including TdT, CD34, and CD117." (PMID 36362518, 2022). "All T-cell lymphoma patients were included in the CHOP group, though tumor origin did not affect the CD34+ cell mobilization yield (P = 0.061)." (PMID 26370464, 2015).
astrocytoma (7 papers, 2012 to 2023). "Two studies compared labelling of CD31 and CD34 for identification of endothelial vessels in astrocytoma tissue, with one study finding that CD34 provided more distinct labelling, and the other noting similar results with both markers." (PMID 36823554, 2023). "Of note, in the literature one example utilizing the difference in staining of CD34 and αSMA is to improve diagnosis in astrocytoma, something that is beyond the scope of the present manuscript." (PMID 23724146, 2013). "There was a significant correlation between CD34 positive and C4d positive endothelial area fraction in diffusely infiltrating astrocytomas (p < 0.001, Pearson correlation)." (PMID 23199209, 2012). "We also found a correlation between the CD34 positive area fraction and C4d positive endothelial area fraction in diffusely infiltrating astrocytoma samples." (PMID 23199209, 2012). "A significant correlation between the CD34 positive endothelial area fraction and C4d positive endothelial area fraction was found in the diffusely infiltrating grade II-IV astrocytomas (r = 0.381, p < 0.001, Pearson Correlation)." (PMID 23199209, 2012). "CD34 is also immunopositive in glioneuronal tumors and immunonegative in infiltrative astrocytoma." (PMID 36290809, 2022). "The expression of CD34 can be observed in some LEATs, such as GG, DNET, and astrocytoma, and is also identified in regional cortical dysplasia which is associated with FCD." (PMID 35372027, 2022). "Analysis of chromosomal copy number alterations (CNAs) in a cohort of 61 patients with LEAT (specified as GG without reference to CD34) revealed gains of chromosomes 7 and 5 as common aberrations, the last being more frequent in LEAT compared to astrocytomas WHO grade II." (PMID 24858213, 2014).
basal cell carcinoma (7 papers, 2016 to 2026). A carcinoma involving the basal cells. "The pattern of CD34 immunohistochemical distribution has been studied in various types of basal cell carcinoma as well, mainly as a differential diagnostic marker in relation to other epithelial skin tumors, and in the context of the histological architecture of the BCC tumor stroma." (PMID 41597444, 2026). "Several authors have noted the presence of stromal cells expressing CD34 in tumors deriving from hair follicles, mainly to differentiate them from basal cell carcinoma." (PMID 34298962, 2021). "The main objective was to assess whether the CD34 staining pattern was useful for the differential diagnosis between basal cell carcinoma and trichoepithelioma." (PMID 34298962, 2021). "However, other extensive observations have shown CD34 expression in stromal cells in trichoepithelioma (76%) and basal cell carcinoma (46%)." (PMID 34298962, 2021). "Immunohistochemistry revealed focally positive BerEP4, CD34-positive stroma, negative androgen receptor, and positive bcl-2, consistent with trichoblastoma and distinguishing the tumor from basal cell carcinoma." (PMID 42196849, 2026). "The hypothesis of this study centered on exploring the potential correlations between dermatoscopic features and the expression of specific immunohistochemical markers (CD34, CD31, Melan A, and D2-40) in Basal Cell Carcinoma (BCC)." (PMID 39399171, 2024). "Initial studies were very promising for distinguishing both entities, since CD34 was negative in basal cell carcinoma or stronger in trichoepithelioma." (PMID 34298962, 2021).
colorectal adenocarcinoma (7 papers, 2012 to 2025). The most common type of colorectal carcinoma. "The average values of non-proliferative (CD34+/Ki67−) vessels in the primary tumor of colorectal adenocarcinoma were: 4 (well-differentiated), 20 (moderately differentiated), and 12 (poorly differentiated)." (PMID 36826036, 2023). "In colorectal adenocarcinoma (CRC), normal colonic stroma harbor CD34+ fibrocytes, whereas this cell population is absent from the stroma of invasive adenocarcinoma." (PMID 23166536, 2012).
diabetic retinopathy (7 papers, 2010 to 2022). "Another study showed CD34 + cells alter molecular pathways associated with diabetic retinopathy pathogenesis and preserve retinal vasculature." (PMID 32493344, 2020). "A previous study has shown that intravitreal injection of human CD34+ cells resulted in retinal homing and integration of these human cells with preservation of the retinal vasculature in diabetic retinopathy." (PMID 35223834, 2022). "More recently, preclinical studies have shown that human CD34+ cells rapidly home into the damaged retinal vasculature in diabetic retinopathy or retinal acute ischemia-reperfusion injury following intravitreal injection and can repair retinal damage." (PMID 35223834, 2022). "The in vivo vasoreparative function of PAI-1 PMO modified CD34+ cells was evaluated using a mouse model of I/R injury that recapitulates many features of diabetic retinopathy, including the presence of acellular capillaries." (PMID 24223881, 2013). "In addition, another study reported increased circulating EPCs expressing CD34/CD133 in patients with diabetic retinopathy." (PMID 20596251, 2010). "Restoration of miR-92a levels in CD34(+) cells from DM patients with diabetic retinopathy reduced the inflammatory phenotype of these cells which suggested that restoring levels of miR-92a could enhance the usefulness of CD34(+) cells in autologous cell therapy." (PMID 33255227, 2020).
glioneuronal tumors (7 papers, 2022 to 2025). "We did not observe higher than background-level CD34 staining (eFigure 3M-P in Supplement 1), further confirming that Ras/Raf/MAPK variants can be present at low VAFs in the affected temporal lobe in the absence of a glioneuronal tumor detected radiographically or histopathologically." (PMID 37126322, 2023).
glomus tumor (7 papers, 2012 to 2025). A rare benign or malignant mesenchymal neoplasm arising from cells that resemble the modified smooth muscle cells of the glomus body. "In conclusion, our series highlights the importance of recognizing mGTs as a rare but distinct histological variant of glomus tumors, characterized by frequent CD34 expression on immunohistochemistry." (PMID 41300877, 2025). "Conclusions: mGTs represent a rare but distinct histological pattern within the glomus tumor spectrum; frequent CD34 expression and mast cell infiltration appear to be characteristic features, although their biological significance remains uncertain." (PMID 41300877, 2025). "Previous studies reported that some glomus tumors showed extensive myxoid stromal degeneration similar to the present case; moreover, they also suggested that marked myxoid stromal change was correlated with co-expression of actin and CD34 in tumor cells." (PMID 30253798, 2018). "As controls, 8 glomus tumors without myxoid features were also examined for CD34 expression." (PMID 41300877, 2025). "However, glomus tumors are negative for CD34, GATA3, and CD117." (PMID 39568313, 2025). "Immunohistochemistry results for CD117, dog-1, and CD34 are positive, and SMA is positive but not as strongly as in glomus tumors." (PMID 32337257, 2020).
invasive carcinoma (7 papers, 2002 to 2025). A carcinoma that is not confined to the epithelium, and has spread to the surrounding stroma. "Several studies have shown the loss of CD34 fibrocytes to be a feature of stromal alterations associated with invasive carcinomas of the breast." (PMID 23469238, 2013). "In DCIS associated with invasive carcinoma, there were significantly greater numbers of CD34+ and CD141+ vessels and fewer staining for vWF compared with pure DCIS." (PMID 11953822, 2002). "Ductal carcinoma in situ associated with invasive carcinoma showed a profile of vascular immunostaining similar to that of pure ductal carcinoma in situ but there were significantly greater numbers of CD34+ and CD141+ vessels and fewer staining for vWF." (PMID 11953822, 2002). "Moreover, some studies found that loss of CD34+-fibrocytes was frequently observed in other types of invasive carcinoma (e.g., invasive lobular carcinoma of the breast and invasive cervical carcinoma)." (PMID 35712477, 2022). "In all cases, the stroma of invasive carcinomas showed a complete loss of CD34 fibrocytes." (PMID 23469238, 2013). "Periductal vascular density and phenotype were determined using morphometry and a panel of anti-endothelial antibodies (von Willebrand factor, CD31, CD141 and CD34) and related to the presence of invasive carcinoma and other histological features." (PMID 11953822, 2002). "However, this hypothesis remains controversial, with some authors describing the loss of CD34 fibrocytes in the absence of SMA myofibroblastic-like cells in the stroma of invasive carcinoma." (PMID 23469238, 2013). "In normal lobules surrounding cases of pure DCIS, MVD was highest when stained with vWF, whereas the normal lobules surrounding areas of invasive carcinoma and DCIS had the highest MVD with CD34." (PMID 11953822, 2002). "In DCIS with invasive carcinoma, in common with cases of pure DCIS, there was an increase above normal in CD31, CD34 and CD141 but a decrease in vWF immunopositive vessels." (PMID 11953822, 2002). "The distribution of CD34 fibrocytes and SMA myofibroblasts has been studied by immunohistochemistry in 41 lymph node and 36 liver metastases from patients with invasive carcinoma of no special type." (PMID 25339428, 2014). "The greater density of CD34+ and CD141+ vessels around ductal carcinoma in situ associated with invasive carcinoma could reflect a greater predisposition to invade but a direct effect of co-existent invasive carcinoma cannot entirely be ruled out in the present study." (PMID 11953822, 2002). "In conclusion, the greater density of CD34+ and CD141+ vessels around DCIS associated with invasive carcinoma could reflect a greater predisposition to invade but a direct effect of co-existent invasive carcinoma cannot entirely be ruled out in the present study." (PMID 11953822, 2002).